OR10J3 (olfactory receptor family 10 subfamily J member 3 (gene/pseudogene))
Description:
Odorant receptor.
Synonyms: formerly OR10J3P
Gene: Protein-coding gene on chromosome 1 (159,313,720 to 159,314,659, reverse strand). Ensembl gene ENSG00000196266.
Subcellular location: Cell membrane
Pathways (Reactome):
Sensory Perception: Expression and translocation of olfactory receptors
Genetic constraint (gnomAD): Missense variants: 449 observed, 395.43 expected, observed/expected ratio (o/e) 1.14, 90% interval 1.05 to 1.23. Synonymous variants: 159 observed, 154.53 expected, observed/expected ratio (o/e) 1.03, 90% interval 0.9 to 1.17.
Homologues: Orthologues: rabbit OR10J3 (81% identical), mouse Or10j3 (80% identical), pig OR10J3 (80% identical), rat Or10j3 (80% identical), rat Or10j3b (75% identical), guinea pig OR10J3 (75% identical), mouse Or10j3b (75% identical). Paralogues in human: OR10J1 (62% identical), OR10J5 (58% identical), OR10R2 (50% identical), OR10J4 (50% identical), OR10T2 (48% identical), OR10Z1 (48% identical), OR10K1 (46% identical), OR10K2 (44% identical), OR1L1 (38% identical), OR2A1 (38% identical), OR2A42 (38% identical), OR1E1 (38% identical), and 116 more.
Diseases named in the same sentence as OR10J3 in open-access papers:
OR10J3 is named in the same sentence as 2 diseases in open-access papers, as found by Europe PMC text mining. Sharing a sentence is not in itself a finding about the gene and the disease. The quoted sentences say what the papers report.
breast carcinoma (1 paper, 2015). "The most up-regulated signalłing gene was OR10J3, involved in innate immunity and associated with risk for breast cancer in women." (PMID 26011631, 2015).
Obesity (1 paper, 2024). Accumulation of substantial excess body fat. "Elevated MCP-1 levels are known to be present in chronic inflammatory diseases, including obesity, indicating a potential association between the OR10J3 gene and obesity." (PMID 39517154, 2024). "Additionally, the OR10J3 gene has been linked to tumor necrosis factor (TNF), which induces inflammation related to obesity." (PMID 39517154, 2024).